IL1B (interleukin 1 beta)
Diseases named in the same sentence as IL1B in open-access papers (continued):
Sharing a sentence is not in itself a finding about the gene and the disease.
asthma (continued). "Specific to asthma, macrophages engaged with fibroblasts via the IL1B signaling pathway, and IL1B was identified as a target gene of macrophages regulated by fibroblasts, which exhibited particularly significant up-regulation in the Int Macro." (PMID 38317239, 2024). "It is possible that in the development of asthma, the IL-1β and IL-18 secreted from eosinophils that undergo pyroptosis help drive the progression of airway hypersensitivity and inflammation." (PMID 39611173, 2024). "Once we demonstrated that RV-induced inflammasome activation is augmented in patients with asthma, we also looked at the baseline status of IL-1β expression and the influence of infection on the inflammasome priming step in both groups." (PMID 37087523, 2023). "Increased NLRP3 and IL-1β responses correlate with increased neutrophil numbers, severity of airflow obstruction, and reduced asthma control in patients, the majority of which were on ICS maintenance therapy." (PMID 38044426, 2023). "We found higher expression of IL-1β in the epithelial areas of the bronchial biopsies of patients with asthma at baseline as compared to healthy controls." (PMID 37087523, 2023). "Accumulating clinical and experimental evidence strongly implicate excessive NLRP3 inflammasome activation and IL-1β production in severe asthma pathogenesis, particularly, neutrophil-high, T2-low subtypes." (PMID 38044426, 2023). "In line with its gene expression in bronchial brushings, we noted a decrease in IL-1β protein expression following RV infection in healthy controls, in contrast to the permanent upregulation of IL-1β in patients with asthma." (PMID 37087523, 2023). "Since IL-1β expression has also been correlated with neutrophilic airway inflammation in patients with severe, steroid-resistant asthma, it has been suggested that it plays a significant role in the pathogenesis of this disease subtype." (PMID 37759430, 2023). "LPS + nigericin-induced IL-1β release from PBMCs from patients with severe asthma positively correlated with both total eosinophilic and neutrophilic inflammatory cell numbers in sputum." (PMID 38044426, 2023). "The assembled NLRP3 inflammasome cleaves pro-Caspase-1 proteolysis into mature Caspase-1 to promote the release of the inflammatory factors IL-1β and IL-18, mediating immune imbalances in asthma." (PMID 38029078, 2023). "We previously showed that respiratory infections have important roles in initiating immune responses, including NLRP3 inflammasome-mediated IL-1β responses, in the asthmatic lung that promote severe, steroid-insensitive asthma." (PMID 38044426, 2023). "In the current study, ATG5 was positively correlated with TNF-α, IL-1β, IL-6, and IL-17 in adult asthma patients." (PMID 37644509, 2023). "ASM cells contribute to airway remodelling in asthma also through the modulation of the inflammatory process; in fact, these cells are able to release inflammatory cytokines such as IL-1β, TNF-α, IL-5, IL-13 and TGF-β." (PMID 37569787, 2023). "A recent study found ILC3 (IL-17+RORγt+) cells were responsible for the development of airway hyperreactivity (AHR) induced by IL-1β in obese mice asthma model, and blockade of IL-1β abolished the AHR and reduced the number of ILC3 cells." (PMID 36949482, 2023). "We also show that systemic immune cells from patients with severe asthma release more IL-1β following a combination of pathogen (LPS)-induced priming and NLRP3 inflammasome activation compared to cells from patients with non-severe asthma." (PMID 38044426, 2023). "We now show that increased NLRP3 inflammasome-mediated IL-1β release from immune cells from humans with severe asthma can be pharmacologically inhibited with MCC950, demonstrating therapeutic potential for inflammasome inhibition in clinical settings." (PMID 38044426, 2023).
asthma (continued). "We observed higher expression of pro-IL-1β protein in HBECs from patients with asthma at baseline in vitro, in bronchial biopsies in vivo, and a trend of moderate upregulation of IL-1β concentration in bronchoalveolar lavage (BAL) fluid in vivo." (PMID 37087523, 2023). "According to research, Acinetobacter baumanni activates the Nod-like receptor NLRP3 via caspase-1 to promote the release of IL-1β and TNFα from macrophages, thereby inducing asthma." (PMID 37180436, 2023). "RV and UV-RV stimulation further increased expression of pro-IL-1β mRNA and protein, especially in epithelium in asthma." (PMID 37087523, 2023). "The proinflammatory cytokine interleukin (IL)-1β produced by the airway epithelium is thought to play an important role in the pathogenesis of asthma." (PMID 36945930, 2023). "HDM stimulation combined with RV infection, significantly increased mature IL-1β secretion in bronchial epithelium of controls and patients with asthma, yet this effect was much more pronounced in asthma." (PMID 37087523, 2023). "Sputum from neutrophilic asthmatics has been shown to exhibit elevated gene expression of NLRP3, caspase-1 and IL-1β and increased IL-1β protein concentration as compared to samples from eosinophilic asthmatics, patients with mild asthma or healthy controls." (PMID 37598239, 2023). "IL-1β plays a key role in neutrophilic inflammation during viral-induced asthma exacerbations with increased expression of IL-33." (PMID 36501052, 2022). "A recent study suggests that pulmonary TNF-a, IL-1β and IL-6 action can affect airway functioning in asthma." (PMID 35335934, 2022). "Older patients with asthma with elevation of IL-1β, IL-6, and MIP-3a/CCL20 levels were reported to have a greater risk of hospitalization, along with those with IL-6- and IL-23-deteriorated asthma control." (PMID 36291665, 2022). "During the inflammatory response, eosinophils also induce lymphocytes to synthesize and release cytokines such as IL-1β, IL-4, IL-6, and IL-13, which promote and exacerbate asthma attacks." (PMID 36408342, 2022). "At four weeks, later occurrence of AD, CMA, and asthma was positively correlated with calprotectin (r = 0.61), IL-1β (r = 0.58), EDN (r = 0.57), and TGF-β (r = 0.57), and negatively correlated with IL-6 (r = −0.71) and IL-10 (r = −0.61)." (PMID 35628877, 2022). "IL-1β has been shown to induce neutrophilic asthma and IL-33 expression in a mouse model of asthma with viral infection exacerbation, and was a key cytokine in induction of airway smooth muscle hypersensitivity." (PMID 35626330, 2022). "There is little information on the impact of glucocorticoids on IL-1β expression in human asthma and data in animal models are conflicting." (PMID 35013387, 2022). "Inhibition of IL-1β expression during asthma pathogenesis is promising therapeutic potential for treating asthmatic patients." (PMID 35500231, 2022). "IL-1β, the main secretory isomer of IL-1, mediates the development of asthma by differentiating and activating Th2 and Th17 cells." (PMID 35186104, 2022). "Linggan Wuwei Jiangxin formula (LGWWJX) can protect against obese asthma most likely through mechanisms, including the inhibition of the IL-1β/ILC3/IL-17A/AHR axis and the regulation of lipid metabolism." (PMID 36051916, 2022). "In a clinical trial presented as a conference abstract, treatment with canakinumab, a human anti-IL-1β monoclonal antibody, attenuated response to allergens in patients with mild asthma." (PMID 35806353, 2022). "We did not identify significant differences between mild/moderate vs. severe asthma cohorts in BAL protein levels of the pro-inflammatory cytokine IL-1β." (PMID 36245744, 2022). "The pro-inflammatory cytokines IL-1B and IL-6, on the other hand, are reduced in Sarcoidosis exosomes, whereas asthma treatment encourages monocytes to produce pro-inflammatory cytokines and CCL2." (PMID 35928365, 2022).
asthma (continued). "It has been demonstrated that the expression of NLRP3, caspase-1 and IL-1β is enhanced in the lungs of asthma patients and allergen-induced asthmatic mice compared to healthy controls." (PMID 34413860, 2021). "Asthma‐2 (n = 19) combined a pro‐inflammatory signature, with a Th2 and innate immune response with upstream modulators of IL‐1β, TNF, IL‐13, IL‐15, and IFNγ." (PMID 34962717, 2021). "Asthma is characterized by chronic inflammatory infiltration caused by inflammatory cells and immune cells, and inhibition of TNF-α, IL-1β, IL-17, IL-4, and IL-6 contributes to improving asthma." (PMID 35069542, 2021). "Murine studies showed that IFN-γ and IL-1β inhibit ILC2 expansion in RV- induced asthma in baby mice." (PMID 34691038, 2021). "One author found an endotype with solely increased IL-1β and smaller percentage of nasal polyps and asthma." (PMID 34208325, 2021). "IL-1β levels are higher in the serum and induced sputum of symptomatic asthmatics than in asymptomatic patients, while in rodent models of asthma, IL-1β is increased and contributes to airway inflammation." (PMID 34572965, 2021). "Gene expression of NLRP3, IL-1β, and caspase-1 are detected at high levels in sputum and peripheral blood of asthma patients with neutrphilic airway inflammation." (PMID 33418879, 2021). "Given the Arf6-dependent asthma-like allergic inflammation, we next examined IL-1β secretion in the OVA-challenged macrophage-Arf6 cKO mice." (PMID 34423792, 2021). "Of interest, IL-1β signaling has been shown to be critical in inducing neutrophil chemotactic factors, IL-33, and Muc5ac expression at viral-induced asthma exacerbation." (PMID 34868022, 2021). "Emerging evidence shows excess IL-1β release in patients with severe asthma, suggesting that IL-1β pathway inhibition is an attractive therapeutic target for severe asthma." (PMID 34423792, 2021). "A large integrative study of asthma transcriptomics in various tissues revealed organism-wide changes in IL-1β and ERK signaling." (PMID 34332619, 2021). "Experimental models trying to reconcile the observations of NTHi and neutrophilic inflammation in cohort studies have shown that suppression of IL-1β-mediated responses prevented the development of the steroid-resistant features of asthma." (PMID 35386999, 2021). "IL-37 attenuated the development of IL-1β, IL-6, and TNF-α in sputum cells (LPS-stimulated) in asthma patients and caused suppression of IL-17 production more notably in patients with asthma than in healthy controls." (PMID 34516405, 2021). "Cytokines (IL‐6, TNF‐α, and IL‐1β) by bronchial epithelial cells promotes the development of asthma." (PMID 34342160, 2021). "In this study, imiquimod decreased gene expression of cytokines of special interest in asthma pathogenesis such as IL-33 and IL-1β." (PMID 34950134, 2021). "miR‐223 was participated in the regulation of neutrophilic airway inflammation through inhibiting the activation of NLRP3/IL‐1β signaling pathway in the asthma model." (PMID 33332758, 2021). "The inflammatory process also involves the synthesis of pro-inflammatory cytokines such as IL-1β, IL-6, TNFα, and TGFβ, which also contribute to asthma pathogenesis." (PMID 33418879, 2021). "Our study provides key evidence that asthma is exacerbated by IL-1β production from macrophages through a prion-like transmission of the extracellular ASC specks." (PMID 34423792, 2021). "Patients with asthma had significantly higher levels of IL-1β (19.74±16.77 vs. 2.63±5.22 pg/mL), IL-6 (7.55±8.65 vs. 2.37±2.47 pg/mL), and TNF-α (12.70±12.03 vs. 4.82±3.97 pg/mL) than the controls." (PMID 33503170, 2021). "The levels of IL-1β, IL-8 and neutrophils were significantly elevated in the sputum of patients with severe asthma, and there was a positive correlation among them." (PMID 34635022, 2021).
asthma (continued). "In contrast, the concentrations of IL-1β in the supernatants of PBMCs infected with RV1B were significantly higher in children with asthma than in the healthy controls (P<0.05)." (PMID 34220812, 2021). "Patients with asthma had significantly higher levels of IL-1β (19.74±16.77 vs. 2.63±5.22 pg/mL), IL-6 (7.55±8.65 vs. 2.37±2.47 pg/mL), and tumor necrosis factor-α (12.70±12.03 vs. 4.82±3.97 pg/mL) compared with the controls." (PMID 33503170, 2021). "Development of steroid-resistance in asthma has been linked to increased NLRP3, caspase-1, and IL-1β responses to NTHi infection." (PMID 35386999, 2021). "HDM-induced IL-1β and IL-6 production were significantly lower in children with asthma than healthy controls (P<0.001)." (PMID 34220812, 2021). "The comparison between groups revealed that moMφs after UPM stimulation produced higher amount of IL-1β protein in asthma group compared to controls (p = 0.004)." (PMID 34168212, 2021). "In conclusion, SC can reduce the inflammatory infiltration in the lung tissues of asthma and suppress the release of inflammatory cytokines, including IL1b and Tnf." (PMID 32016112, 2020). "In particular, the IL-1 receptor antagonist anakinra and the anti-IL-1β monoclonal antibody canakinumab are currently under clinical investigation in phase I/II trials enrolling patients with mild asthma." (PMID 33329598, 2020). "Using multiplex xMAP technology, we have further validated that the levels of the upstream cytokines of S1P signaling such as IL-13, IFN-γ, TNF-α, IL-4, IL-5, and IL-1β were increased in the serum of asthma patients." (PMID 32637407, 2020). "There was a significant increase in the corresponding IL-1β and IL-8 levels in patients with severe asthma." (PMID 32998415, 2020). "Another pro-inflammatory cytokine, IL-1β, is also been suspected of involvement in the pathogenesis of sex-specific allergic diseases in adult male asthma patients." (PMID 32883301, 2020). "In sputum of neutrophilic asthma patients excessive inflammasome activation and production of IL-1β have been found, which correlate with neutrophil counts in lung tissue and sputum, asthma severity, and steroid resistance in asthma." (PMID 32509795, 2020). "The expression level of Th1 mediated cytokines, such as TNFα, and IL-1β were significantly higher in ACO cases with respect to asthma and controls." (PMID 32448302, 2020). "The upstream regulator cytokines of S1P signaling such as IL-13, IFN-γ, TNF-α, IL-4, IL-5, and IL-1β were significantly (P < 0.01) increased in the serum of asthma patients compared the healthy controls." (PMID 32637407, 2020). "Similar patterns of expression of known gene signatures were observed in endobronchial biopsies characterized by the upregulation of DNASE1L3 in asthma and IL1B in neutrophilic asthma suggesting these pathways are relevant in both biopsy and sputum in asthma." (PMID 31903716, 2020). "Inhibition of IL-1β activity by administration of neutralizing antibody or deletion of the IL-1 receptor type I abrogated the progression of asthma, and administration of recombinant IL-1β replicated the markers of neutrophilic asthmatic inflammation." (PMID 32423405, 2020). "The expression of IL1b and Tnf was significantly increased in the asthma group compared to that in the sham control group." (PMID 32016112, 2020). "Upregulation miR-223 can inhibit the airway inflammation and pro-inflammatory cytokines production through inhibiting the activation of NLRP3/IL-1β signaling pathway in mice, which is involved in the pathogenesis of asthma." (PMID 32423405, 2020). "Gene expression of DNASE1L3 (P = .045) was upregulated in asthma compared with HC, and IL1B (P = .017) was upregulated in neutrophilic asthma compared with non‐neutrophilic asthma." (PMID 31903716, 2020). "We have demonstrated upregulation of DNASE1L3 in asthma compared with HC and IL1B in neutrophilic compared with non‐neutrophilic asthma." (PMID 31903716, 2020).
asthma (continued). "As inflammation is widely associated with asthma symptoms, we measured the inflammatory indicators in BALF, including IL-1β, IL-6, TNF-α, TGF-β, and IFN-γ." (PMID 33456673, 2020). "The cytokines that comprise part of the Th17 response (IL-1β and IL-17A) and are important in promoting the secretion of pro-inflammatory cytokines were significantly elevated in RV-C-infected children with asthma compared to controls." (PMID 31703379, 2019). "Several pulmonary diseases including asthma, acute lung injury, COPD and acute respiratory distress syndrome (ARDS), are associated with abnormal TNF-α, IL-1β and IL-6 expression." (PMID 31395940, 2019). "Further, oxidative stress induced protein levels of IL-1β upon poly(I:C) stimulation, a cytokine which is involved in driving inflammation and a predictor for future asthma exacerbations." (PMID 31849956, 2019). "Both Dexa and MYR decreased the level of IL-1β in the lung tissue (P < 0.01, P < 0.05) and in serum (P < 0.05) compared to the asthma group." (PMID 32641957, 2019). "As a result, MYR with the reduction of IL-1β, the key interleukin, can be effective in the treatment of asthma." (PMID 32641957, 2019). "Serum YKL-40 positively correlated with non-T2 inflammatory signatures such as IL-1β and IL-6, which predicts insensitive responses to asthma treatment." (PMID 31113430, 2019). "It demonstrates that IL-1β can be a biomarker for active allergic diseases such as AR, asthma, and atopy." (PMID 31548841, 2019). "IL-1β is an important inflammatory molecule shown to have roles in asthma and COPD, and IL-1β knockout mice have reduced neutrophilic and Th2 responses in a murine asthma model." (PMID 30333178, 2019). "Currently, there is little information on any clinical effects of IL-1β active drugs on asthma exacerbations." (PMID 29361942, 2018). "By contrast, the present data suggested involvement of IL-1β, at viral induced asthma exacerbations." (PMID 29361942, 2018). "IL-1β has recently been discussed in severe asthma and in relation to exacerbations of chronic obstructive pulmonary disease (COPD) and asthma." (PMID 29361942, 2018). "IL-1β is a pro-inflammatory cytokine with increased expression in asthma, COPD, and CF bronchiectasis." (PMID 30380761, 2018). "Little is known about the involvement of IL-1β in Th2-upstream cytokine expression at exacerbation of asthma." (PMID 29361942, 2018). "IL-1β has also been shown to be upregulated in neutrophilic asthma compared to eosinophilic and pauci-granulocytic asthma." (PMID 30380761, 2018). "We suggest that IL-1β has a role both in neutrophilic and Th2 inflammation at viral-induced asthma exacerbations." (PMID 29361942, 2018). "Immune and epithelial cells of the lung can respond to inhaled substances by the release of central mediators of asthma, such as IL-4 and IL-13, as well as inflammatory mediators, such as IL-1β, and immune cell attracting proteins, such as Mcp-1." (PMID 29614747, 2018). "The experimental exacerbation of asthma exhibited IL-1β-dependent features of neutrophilic lung inflammation as well as Th2-upstream cytokines." (PMID 29361942, 2018). "The expression of serum IL-1β, IL-4, and IL-17F were all significantly increased in the asthma model animals when compared with levels in mice from the PBS + PBS group (P < 0.05, P < 0.01, and P < 0.001, respectively)." (PMID 30089474, 2018). "In this study, the expression of IL-1β in LPS-stimulated U937 Cells, in serum and in the lung tissue of asthma mice was all detected." (PMID 29311942, 2017). "In the present study, we investigated vitamin D3 levels, airway hyper-responsiveness, cytokine levels, and NLRP3 and IL-1β mRNA expressions by developing a mouse model of obese asthma via OVA-challenge and high-fat diet." (PMID 29160418, 2017). "In the obese asthma group, IL-1β expression levels were largely increased compared with the normal control group (P<0.05)." (PMID 29160418, 2017).